INS (insulin)
Diseases named in the same sentence as INS in open-access papers (continued):
Sharing a sentence is not in itself a finding about the gene and the disease.
tumor (continued). "Insulin plays a central role in metabolic regulation and its signaling component mTOR also plays important roles in tumor growth." (PMID 25792980, 2015). "Conversely, CR diet exhibited less tumor burden with a significant reduction in levels of insulin, IGF-1 and inflammation markers." (PMID 25895126, 2015). "These combined data suggest that pro-mitogenic insulin analogues drive tumor formation that is dominated by either p-Erk and/or p-Akt, although at this point we cannot exclude the activation of additional signaling pathways." (PMID 25848982, 2015). "In this study, we demonstrate that metabolic stresses including insulin/IGF-1 enhance expression of TRB3 in a diversity of human tumour tissue and cells." (PMID 26268733, 2015). "Consistently, 2-DG, in non-tumor as well as tumor bearing mice, reduced the blood glucose and insulin levels suggesting an improved glucoregulation or better glucose homeostasis." (PMID 26135741, 2015). "Functional enrichment analysis of putative and validated miRNA targets highlighted cellular processes such as tumor suppression, anti‐inflammatory response, and modulation of Wnt, insulin, mTOR, and MAPK signaling pathways, among others." (PMID 26176567, 2015). "Our data fit a model in which eIF6-driven translation is a targetable feed-forward loop that induces insulin resistance and tumour growth." (PMID 26383020, 2015). "Through this pathway, Hippo-sensitized Ras/Src-activated cells are positioned to efficiently respond to insulin signals and promote tumor overgrowth." (PMID 26573956, 2015). "The protective effects of eIF6 depletion on tumour growth and the specific action of eIF6 on insulin-stimulated translation suggest that eIF6 and 60S availability control the translation of specific mRNAs." (PMID 26383020, 2015). "The data suggest that short-term administration of metformin in this setting has anti-tumor effects significantly involving the indirect, insulin-dependent pathway." (PMID 26111812, 2015). "Several animal studies showed that PCa xenograft mice fed with HFD had more increased tumor growth and shorter survival time, accompanied with higher serum insulin and IGF-1 levels." (PMID 25722971, 2015). "Metformin decreases tumor cell proliferation by improving insulin sensitivity and reducing hyperinsulinaemia." (PMID 26114294, 2015). "We conclude that SIKs couple nutrient (insulin) availability to Yki-mediated evasion of insulin resistance and tumor growth, ensuring Ras/Src-tumor growth under nutrient favorable conditions." (PMID 26573956, 2015). "Recently, it is found that the H. sinensis has activities to modulate immune responses, inhibit tumour cell proliferation, enhance hepatic function, regulate insulin sensitivity and decrease plasma cholesterol levels." (PMID 25765329, 2015). "SIK activity promotes Ras/Src-activated cells to efficiently respond to upstream Hippo signals, ensuring tumor overgrowth in organisms that are otherwise insulin resistant." (PMID 26573956, 2015). "The analysis in individual patients to correlate several biomarkers (serum insulin, and tumor IR and p-Akt, with tumor Ki-67) is a compelling one." (PMID 26111812, 2015). "An antibody with neutralizing activity against both IGF-IR and IGF-I/insulin-hybrid receptors showed more potent anti-tumor effects than antibodies targeting only the IGF-IR or hybrid receptors in xenograft models." (PMID 26074875, 2015). "Investigations revealed highly elevated cortisol levels (the levels having previously been normal) with markedly raised ACTH levels, consistent with the co-secretion of ACTH and insulin by the tumour." (PMID 24683485, 2014). "The decrease in insulin levels caused by metformin can reduce the activation of insulin pathways such as PI3K/Akt/mTOR and MEK/ERK1/2 and lead to a decrease in tumor growth." (PMID 24858012, 2014).
tumor (continued). "Most of these studies have attributed the tumor inhibitory effect of CR to the deceased circulating levels of insulin and IGF-1 and inhibition in its subsequent downstream signaling of PI3K/Akt-mTOR." (PMID 25026276, 2014). "In mice and humans, Trib3 levels are regulated by nutrient availability in skeletal muscle cells, beta-cells, adipocytes, and tumor cells, highlighting a possible role in the regulation of metabolic flux in insulin-sensitive tissues." (PMID 25329475, 2014). "Further, the neuroendocrine and insulin secreting nature of the tumour was confirmed ex vivo by histopathological examination, immunohistochemistry and ultra-structural examination." (PMID 24741994, 2014). "Metformin can have a direct antitumoral effect, but also can act indirectly to improve insulin sensitivity, decrease hyperinsulinaemia and consequently decrease tumor proliferation." (PMID 24858012, 2014). "More importantly, this study links Sir2 family proteins to insulin/IGF signaling in drug-induced stress resistance in neoplasia." (PMID 24885964, 2014). "We also extensively reviewed literature for similar cases of ectopic insulin secreting tumours published previously." (PMID 24741994, 2014). "Additional studies have demonstrated intensified insulin signaling when IGF1R is interrupted in tumor cells." (PMID 24434591, 2014). "Other explanations proposed relate to metformin’s well-known effects on cholesterol, leptin, insulin levels and adiponectin, suggesting that some metabolic changes account for a reduction in tumor growth." (PMID 25215935, 2014). "A number of authors have used Ce6 for conjugation with either tumor specific monoclonal antibodies, or in peptide mediated approaches with insulin or transferrin." (PMID 25111655, 2014). "Recent studies have demonstrated that the anti-diabetic drug, metformin, can exhibit direct antitumoral effects, or can indirectly decrease tumor proliferation by improving insulin sensitivity." (PMID 24858012, 2014). "The effects of insulin and hyperinsulinaemia on tumorigenesis are thought to be mediated by the insulin receptor, which is expressed in both normal tissues and tumours 81–82." (PMID 23668396, 2014). "Ectopic insulin producing tumours located away from pancreatic beds are infrequently reported in literature." (PMID 24741994, 2014). "TSC2, also known as tuberin, specifically has been shown to be involved in insulin signaling, tumor suppressor functions, and regulation of cell growth." (PMID 25541970, 2014). "SH2-containing inositol 5′-phosphatase 2 (SHIP2), which generally regulates insulin signaling, cytoskeleton remodeling, and receptor endocytosis, has been suggested to play a significant role in tumor development and progression." (PMID 25525286, 2014). "Similar to our case, the patient first presented with symptoms related to the presence of an insulin-producing tumour, followed by symptoms related to ectopic secretion of ACTH." (PMID 24683485, 2014). "The INS-1 cell line was widely used for insulin secretion researches, which was established from radiation induced tumor growing in medium with 2-ME (β-mercaptoethanol)." (PMID 25294221, 2014). "Infections are initiated through establishment of parasite larvae within the intermediate host’s liver, where high concentrations of insulin are present, followed by tumour-like growth of the metacestode in host organs." (PMID 24468049, 2014). "Cul2 is part of the VHL tumor suppression complex that ubiquitinates HIF1α; the disruption of HIF1α has been found to improve the insulin sensitivity and decrease adiposity in mice." (PMID 24628878, 2014). "The effect of insulin was also studied on anonymized samples from healthy lung tissue surrounding the tumor obtained from patients during lung resection." (PMID 25278226, 2014). "A striking result was mortality from neoplasms; an increase in mortality emerged in almost every age group of insulin treated women." (PMID 23837500, 2013).
tumor (continued). "The range of activities of these compounds extends from anti-tumour, febrifugal, virucidal, anti-insulin, antibacterial, prostate treatment, vaccine constituents to anti-hypercholesterolemic." (PMID 23777548, 2013). "Concomitantly, we also observed that activation of Insulin/IGF-I signaling pathways leads to an increased tumor cell invasion." (PMID 24282611, 2013). "Apart from direct actions of insulin and high glucose, various metabolic dearrangements, parallel to DM, can contribute to development of tumor." (PMID 23476808, 2013). "In this context, it was demonstrated that tumor growth in human tumor xenograft models was significantly reduced by using antibodies that inhibit the Insulin/IGF-I signaling." (PMID 24282611, 2013). "Corroborating this result, stimulation with insulin and IGF-I also increased the fibronectin expression at the protein level, which has been closely associated with tumor cell invasion." (PMID 24282611, 2013). "PKM2, a critical enzyme for aerobic glycolysis and tumor growth, was also up-regulated by insulin treatment." (PMID 23762265, 2013). "So, insulin can also promote tumor cell growth indirectly through elevated levels of circulating IGF-1 and sex steroids." (PMID 24224094, 2013). "One comes from biological factors (e.g., tumor's size/configuration changes, plasma substrate level, insulin level, and input function variations)." (PMID 23841937, 2013). "Consistent with the immunohistochemistry staining of PDICs, we found that this tumor had corresponding absences of insulin and MafA expression." (PMID 23691228, 2013). "Because of this, insulin and IGF-I can interact either with IR or with IGF-IR, and both of these receptors have been associated with tumour development." (PMID 24073332, 2013). "Klotho is observed in several tumors to induce cell apoptosis and inhibit tumor growth through inhibiting insulin/IGF-1 signaling by inhibiting the tyrosine phosphorylation of IGF-1 receptor." (PMID 23432957, 2013). "Direct mitogenic effect of insulin on tumor cells is mediated through the insulin receptors that are expressed on tumor cells." (PMID 24224094, 2013). "The combination therapy (CR/Ab) further decreased final tumor weight and proliferation, increased apoptosis in comparison to the Ad-lib group, and lowered plasma insulin levels relative to the Ad-lib and Ad-lib/Ab groups." (PMID 23823800, 2013). "Results showed that CR alone decreased final tumor weight, plasma insulin and IGF-1 levels, and increased apoptosis." (PMID 23823800, 2013). "Apart from normalising systemic insulin, the intracellular effects of metformin in tumour cells have been the subject of recent study and review." (PMID 23573093, 2013). "In future studies it would be relevant to examine how constant exposure to lower, more clinical relevant, doses of insulin and insulin analogs would influence tumor growth in our short-term model." (PMID 24260289, 2013). "There is evidence that the mitogenic response to insulin is more pronounced after activation of isoform A of the insulin receptor, which is overexpressed in some tumour cells, than after activation of isoform B of the receptor." (PMID 23983688, 2013). "For example, klotho is observed to induce cell apoptosis and inhibit tumor growth through inhibiting insulin/ insulin-like growth factor-1 (IGF-1) signaling." (PMID 23432957, 2013). "Immunohistochemistry of the primary tumour a year prior revealed focal positivity for serotonin, as well as insulin, glucagon, and pancreatic polypeptide." (PMID 23476666, 2013). "In vitro studies have shown that glargine is more mitogenic than human insulin and promotes proliferation of certain tumor cells." (PMID 24278227, 2013). "For insulin treated, relative overall excess mortality remained unchanged and mortality from neoplasms increased among women." (PMID 23837500, 2013).
tumor (continued). "It will be interesting in future studies to investigate an extensive panel of endocrine markers in MLPs, including insulin and several of the beta-cell specific genes analyzed here, to definitively determine if MLPs and PDICs are the same class of tumor." (PMID 23691228, 2013). "A decision was made in favour of withdrawing octreotide and giving her oral everolimus treatment with radiotherapy to the primary tumour, which was considered as a significant source of endogenous insulin secretion." (PMID 23738155, 2013). "Chronically elevated insulin facilitates in tumour tissues increased activation of mitogenic, anabolic, and prosurvival pathways with the increased levels of insulin and concomitant elevated insulin-like growth factor 1 (IGF-1)." (PMID 23573093, 2013). "The tumor cells have a mechanism for capturing glucose that is independent from insulin, which confers a metabolic advantage." (PMID 24138811, 2013). "A statistically significant increase between these two periods was observed in excess mortality from neoplasms both among insulin-treated men and women." (PMID 23837500, 2013). "It has been known for over two decades that glucose is the driving force for tumor cell growth and that high levels of insulin promote metastasis." (PMID 22554284, 2012). "There is a strong need for improved animal models in order to test the tumour-promoting effects of insulin analogues." (PMID 22590494, 2012). "We performed a proliferation assay in order to analyze the influence of both, high glucose and insulin concentrations, as well as inhibition of Akt and PLCγ on the proliferative capacity of the two tumor cell lines." (PMID 22554284, 2012). "While tumor cell switches responding to anabolic hormones: insulin and IGF, support anabolism, powered by oxidative glycolysis that is driven by an active citrate synthase condensation." (PMID 22954255, 2012). "Both serum insulin and visfatin concentrations correlated positively with tumor proliferation and negatively with tumor apoptosis." (PMID 23170114, 2012). "Exogenous insulin increased tumor incidence and tumor multiplicity in rats given the intestinal carcinogen azoxymethane." (PMID 23056418, 2012). "Tumor proliferation correlated significantly with serum insulin (r=0.58, P=0.01) and visfatin concentrations (r=0.51, P=0.02), while it did not correlate with serum glucose concentration (r=0.20, P=0.1)." (PMID 23170114, 2012). "For these reasons, we report about the regulatory functions of Akt and PLCγ regarding tumor cell proliferation and migration under the specific premise of higher than normal glucose and insulin concentrations." (PMID 22554284, 2012). "RIP1-Tag2 mice express the oncogene SV40 T antigen under the control of the rat insulin gene promoter and display distinct stages of tumor progression: onset of hyperproliferation, induction of angiogenesis and formation of solid tumors." (PMID 24213240, 2012). "Although studies from our laboratory and others have shown that insulin promotes primary tumor growth, studies investigating a possible connection between insulin and metastatic events in general are limited." (PMID 22226054, 2012). "In this comment, we suggest that the complex metabolism of tumor cells was a possible consequence of an altered hormonal interaction, between neighboring pancreatic cells involving insulin and other factors released by beta cells." (PMID 22954255, 2012). "As a result of the current knowledge of the effect of insulin on biology of tumor cells several conclusions can be done." (PMID 22649741, 2012). "AKT kinases play a key role in regulating cell survival, insulin signaling, angiogenesis and tumor formation." (PMID 22912686, 2012). "Insulin influences the intracellular metabolism of the tumor cell, which leads to increase of the number of cells in phase S, where they are with highly sensitive to specific chemotherapeutics." (PMID 22649741, 2012).
tumor (continued). "Once available, such models would allow a more detailed correlation between in vitro molecular characteristics and in vivo tumour promoting effects of insulin and insulin analogues." (PMID 22590494, 2012). "The fact that glucose and insulin were strong inducers of tumor cell migration is also reflected by an increase in average distance migrated (ADM)." (PMID 22554284, 2012). "We also observed increased tumor mass and cell proliferation, respectively, suggesting a role for insulin in significantly promoting the growth-mediating effects of c-Myc." (PMID 22226054, 2012). "This demonstrates the potent effect of elevated insulin in advancing the metastatic spread of tumor cells." (PMID 22226054, 2012). "The up-regulation of miR-125b down-regulates its targets and seems to suppress tumor growth and angiogenesis through the insulin/IGFR pathway." (PMID 24212803, 2011). "Apart from the mode of action of insulin on the tumour cells expressing insulin and IGF receptors, we found modulated gene activities for cell cycle regulation, cell-to-cell contact and locomotion when cells were cultured solely at high glucose (11 mM)." (PMID 21179032, 2011). "We observed many factors and pathways affected by MT19c, including some related to tumor growth and survival, such as DNA damage response, apopotic genes, insulin, and PPARγ." (PMID 21781307, 2011). "Regarding the mode of action, IGF-1 pathway plays a role in insulin-related tumor promotion in the colon." (PMID 22174655, 2011). "Using the inhibitors wortmannin (PI3K inhibitor at 250 nM), Go6976 (PKCα inhibitor at 6 nM) and ML-7 (MLCK inhibitor at 10 μM), we were able to track down the key molecules of the signalling cascade of the glucose- and insulin-induced tumour cell migration." (PMID 21179032, 2011). "Nevertheless, since more than two decades it is known that glucose is the driving force for the growth of tumour cells and that increased insulin levels promote metastasis." (PMID 21179032, 2011). "There was, however, a significant drop in blood glucose, insulin and lactate levels, and a positive correlation between blood lactate as well as insulin levels and tumor growth was found." (PMID 22029671, 2011). "This transgenic tumor model carries the SV40 T antigens under control of the rat insulin promoter, which is expressed in the islets of Langerhans in the pancreas." (PMID 21264222, 2011). "Proliferation assays revealed that high levels of glucose (11 mM) and insulin (100 ng ml−1) did promote the proliferation of the tumour cell lines HT29, SW480, MCF-7, MDA MB468, PC3 and T24." (PMID 21179032, 2011). "In those receiving NPH insulin, one patient experienced edema, which disappeared on discontinuation, and a second patient had an injection site skin reaction, also resulting in discontinuation." (PMID 21631903, 2011). "Lkb1 is a known tumor suppressor and a negative regulator of the mTOR/Insulin pathway, which has important roles in autophagy and nutrient sensing, while the Camptothecins function as DNA Topoisomerase 1 (Top1) inhibitors." (PMID 21909362, 2011). "The insulin-independent phenotype described in this report represents a qualitatively different metabolic condition that promotes tumor cell growth." (PMID 21437235, 2011). "In vitro studies have shown that high insulin levels can affect angiogenesis and potentially propagate tumor progression by stimulating the mitogen pathway via both insulin and IGF receptors." (PMID 21773024, 2011). "Pinkston-Gosse and Kenyon have identified 29 daf-16/FOXO-regulated genes that act in the insulin/IGF-1 pathway to influence C. elegans tumor growth." (PMID 21084729, 2010). "Laboratory data, including tumor markers, were within the normal ranges, and her insulin and glucagon levels were also within the normal ranges." (PMID 20825631, 2010).